IGHV4-39 (immunoglobulin heavy variable 4-39)
Description:
V region of the variable domain of immunoglobulin heavy chains that participates in the antigen recognition. Immunoglobulins, also known as antibodies, are membrane-bound or secreted glycoproteins produced by B lymphocytes. In the recognition phase of humoral immunity, the membrane-bound immunoglobulins serve as receptors which, upon binding of a specific antigen, trigger the clonal expansion and differentiation of B lymphocytes into immunoglobulins-secreting plasma cells. Secreted immunoglobulins mediate the effector phase of humoral immunity, which results in the elimination of bound antigens. The antigen binding site is formed by the variable domain of one heavy chain, together with that of its associated light chain. Thus, each immunoglobulin has two antigen binding sites with remarkable affinity for a particular antigen. The variable domains are assembled by a process called V-(D)-J rearrangement and can then be subjected to somatic hypermutations which, after exposure to antigen and selection, allow affinity maturation for a particular antigen.
Synonyms: IGHV439; VH
Tractability: Antibody: its Gene Ontology location is reachable by antibodies, with high confidence; UniProt places it where antibodies can reach, with medium confidence; UniProt predicts a signal peptide or a membrane-spanning region.
Gene: Immunoglobulin variable (V) gene on chromosome 14 (106,421,711 to 106,422,218, reverse strand). Ensembl gene ENSG00000211959.
Subcellular location: Secreted; Cell membrane
Pathways (Reactome):
Immune System: Antigen activates B Cell Receptor (BCR) leading to generation of second messengers; CD22 mediated BCR regulation; Classical antibody-mediated complement activation; FCERI mediated Ca+2 mobilization; FCERI mediated MAPK activation; FCERI mediated NF-kB activation; FCGR activation; Fc epsilon receptor (FCERI) signaling; Immunoregulatory interactions between a Lymphoid and a non-Lymphoid cell; Initial triggering of complement; Regulation of Complement cascade; Regulation of actin dynamics for phagocytic cup formation; Role of LAT2/NTAL/LAB on calcium mobilization; Role of phospholipids in phagocytosis
Disease: FCGR3A-mediated IL10 synthesis; FCGR3A-mediated phagocytosis; Potential therapeutics for SARS
Hemostasis: Cell surface interactions at the vascular wall
Vesicle-mediated transport: Scavenging of heme from plasma
Gene Ontology:
Molecular function: antigen binding
Biological process: immune response; immunoglobulin mediated immune response
Cellular component: extracellular region; plasma membrane
Genetic constraint (gnomAD): Missense variants: 43 observed, 15.91 expected, observed/expected ratio (o/e) 2.7. Synonymous variants: 19 observed, 8.16 expected, observed/expected ratio (o/e) 2.33.
Homologues: Paralogues in human: IGHV4-59 (90% identical), IGHV4-61 (90% identical), IGHV4-28 (86% identical), IGHV4-31 (86% identical), IGHV4-34 (85% identical), IGHV4-4 (85% identical), IGHV4OR15-8 (84% identical), IGHV6-1 (59% identical), IGHV2-5 (54% identical), IGHV2-26 (52% identical), IGHV2-70 (51% identical), IGHV2-70D (50% identical), and 65 more.
Diseases named in the same sentence as IGHV4-39 in open-access papers:
IGHV4-39 is named in the same sentence as 1 disease in open-access papers, as found by Europe PMC text mining. Sharing a sentence is not in itself a finding about the gene and the disease.
IGHV4-39 shares sentences with these, for which no sentence is quoted: cancer (1 paper).